JAK2 (Janus kinase 2)
Diseases named in the same sentence as JAK2 in open-access papers (continued):
Sharing a sentence is not in itself a finding about the gene and the disease.
myeloproliferative neoplasm (continued). "Since JAK2 mutations constitutively activate downstream signaling and are drivers of myeloproliferative neoplasm, the discovery of specific inhibitors of the JAK2 protein has become a research hotspot for the treatment of diseases." (PMID 36144838, 2022). "Five of the 12 patients (42%) comprised disease progression from an underlying myeloproliferative neoplasm (MPN) and showed NGS evidence of a JAK2 V617F mutation." (PMID 36323674, 2022). "One subject, C12, harbored the JAK2 V617F mutation (VAF 0.82%), a clinically relevant variant identified in myeloproliferative neoplasms (MPNs) that has also been associated with ~12-fold increased risk of CVD and thrombosis risk." (PMID 35978153, 2022). "Pathogenic variants in one of the three core genes (i.e., CALR, MPL, and JAK2) are characteristic in the context of sporadic myeloproliferative neoplasms." (PMID 35884491, 2022). "Myeloproliferative neoplasms (MPN) are clonal hematopoietic disorders characterized by the mutations in three types of molecular markers, with emphasis on Janus kinase 2 gene mutation (JAK2V617F)." (PMID 35163413, 2022). "On the other hand, the drugs approved for treatment of myeloproliferative neoplasms target JAK2 and its mutant form (JAK2V617F)." (PMID 35631587, 2022). "Blockade of PFKFB3 by 3PO in mutant JAK2-driven myeloproliferative neoplasms alters redox homeostasis through inhibiting glycolysis, thus, resulting in accumulation of reactive oxygen species and increased apoptosis." (PMID 35155224, 2022). "Myeloproliferative neoplasms (MPNs) are clonal disorders of the hematopoietic stem cell (HSC), caused by somatic mutations in JAK2, MPL, or CALR resulting in increased proliferation of the erythroid, megakaryocytic, and myeloid lineages." (PMID 36100613, 2022). "In patients with myeloproliferative neoplasms in which a constitutive activation of JAK2-dependent signaling occurs, ruxolitinib impairs NK cell function." (PMID 36685552, 2022). "Myeloproliferative neoplasms (MPNs), a class of blood cancers, typically arise from mutations in the thrombopoietin receptor (MPL), JAK2, or calreticulin that constitutively activate JAK/STAT signaling in hematopoietic stem and progenitor cells (HSPCs)." (PMID 35998053, 2022). "HSP90 and JAK2 inhibition was shown to synergistically overcome resistance to JAK2-TKI in human myeloproliferative neoplasm cells." (PMID 35440787, 2022). "These NGS panels target genes that are associated with multiple hematological conditions, e.g., DNMT3A, TET2, ASXL1, and genes that are implicated in the pathogenesis of specific hematological disorders, e.g., JAK2 for myeloproliferative neoplasms (MPN)." (PMID 36290845, 2022). "The JAK2 inhibitor, gandotinib, showed high potency toward the JAK2V617F mutation and showed promising potential in the treatment of myeloproliferative disorders." (PMID 35631587, 2022). "Given the role of JAK2 in maintaining genome stability and its positive correlation with patient survival, caution is warranted when using JAK2 inhibitors for treating myeloproliferative disorders." (PMID 35851582, 2022). "The role of the cytoplasmic tyrosine kinase JAK2 in patients with a myeloproliferative disorder has been extensively investigated." (PMID 35453637, 2022). "The JAK family is a class of non-receptor tyrosine kinases, play an important role in the development of many diseases, especially JAK2, which has been treated as a target of myeloproliferative diseases." (PMID 35382859, 2022). "In some of these rare cases the diagnosis of a JAK2 V617F-positive disease preceded the acquisition of the Ph-chromosome; in others the second myeloproliferative disease emerged in the remission phase of CML." (PMID 35902731, 2022). "Somatic mutations in JAK2, calreticulin, and MPL genes drive myeloproliferative neoplasms (MPN), and recent technological advances have revealed a heterogeneous genomic landscape with additional mutations in MPN." (PMID 34680185, 2021).
myeloproliferative neoplasm (continued). "Combination with HSP90 inhibitors is evaluated as an effective strategy to overcome the resistance of JAK2 inhibitors in fibrotic diseases and myeloproliferative neoplasms." (PMID 35059401, 2021). "The order in which somatic mutations are acquired determines how individual cancers behave, and the order in which JAK2 and TET2 are mutated influences clinical features and response to targeted therapy in patients with myeloproliferative neoplasms." (PMID 33653301, 2021). "The clinical records of the 13 JAK2-positive cases were reviewed, of which 5 were excluded because they corresponded to patients with a known myeloproliferative neoplasm." (PMID 33420222, 2021). "A recent study found that HDAC11 can promote the malignant phenotypes of JAK2-driven myeloproliferative neoplasms." (PMID 34395273, 2021). "We examined AML-43 in detail, which was a case evolving from an antecedent JAK2 + TET2 + myeloproliferative neoplasm (MPN)." (PMID 34021247, 2021). "JAK2 is an important mediator of erythropoiesis and is the most frequent gene implicated in BCR-ABL1-negative myeloproliferative neoplasms." (PMID 34833034, 2021). "Constitutive JAK2 activation provides the basis for the shared clinical features of the myeloproliferative neoplasms." (PMID 33777803, 2021). "JAK2V617F is an activating point mutation resulting in increased JAK2 activity, leads to STAT5 activation, and has been described in the majority of patients with myeloproliferative neoplasms (MPNs)." (PMID 34055801, 2021). "Jak2 was also found to participate in several different types of cancers and myeloproliferative diseases." (PMID 34199353, 2021). "Together with the role of JAK2 in myeloproliferative disorders this led to the development of multiple JAK inhibitors as potential therapeutics." (PMID 33980892, 2021). "Momelotinib is a potent ATP-competitive inhibitor of JAK2, it has been used for targeted therapies of myeloproliferative tumors." (PMID 34199353, 2021). "Mutations in these three genes (JAK2, CALR and MPL) underlie nearly all the three myeloproliferative diseases, and the presence of one or other in ET and MF has prognostic significance." (PMID 35844697, 2021). "Activated Jak2-Stat5 signaling can be readily targeted by the current Jak2-inhibitors that have been developed for myeloproliferative disorders (MPDs) and hematological malignancies, which will be reviewed here." (PMID 34680353, 2021). "One drug used for myeloproliferative neoplasms, Fedratinib, targets the receptors for Janus kinase 2, which is a gene involved with the growth and division of cells." (PMID 32735546, 2020). "In myeloproliferative neoplasms the JAK-STAT signaling pathway can be inhibited with the JAK1/JAK2 inhibitor ruxolitinib and in rheumatoid arthritis with less selective JAK inhibitors such as tofacitinib and baricitinib." (PMID 32188095, 2020). "Polycythemia vera is a myeloproliferative neoplasm characterized by erythrocytosis driven by constitutive activation of the erythropoietin (Epo) receptor by mutant JAK2 protein kinase." (PMID 33364111, 2020). "Acquired activating mutations of JAK2 in hematopoietic tissues, with JAK2V617F as the most common, drive development of myeloproliferative neoplasms (MPNs)." (PMID 32086626, 2020). "In this report, we discuss a case of atypical (asymptomatic) myocardial infarction with secondary thromboembolism in a patient positive for JAK2 V617F with a likely myeloproliferative neoplasm." (PMID 32685224, 2020). "Our case emphasizes two important points: first, need for extensive workup in a patient with unusual site thrombosis including JAK2 analysis and second, investigating for myeloproliferative neoplasm if presented with thrombosis even with normal blood counts." (PMID 32637283, 2020).
myeloproliferative neoplasm (continued). "Myeloproliferative neoplasms (MPN) are a group of clonal malignant bone marrow (BM) diseases, originating from a hematopoietic stem cell (HSC) which acquired a MPN phenotypic driver mutation (i.e., in JAK2, CALR, or MPL), leading to constitutively active JAK-STAT signaling." (PMID 32983162, 2020). "In contrast, JAK2V617F, a constitutive active mutant of Janus kinase 2 (JAK2) that is found in patients with myeloproliferative neoplasms, phosphorylates PRMT5 and downregulates its activity." (PMID 32859041, 2020). "Three patients carried the same gain of function missense variant, c.1849G>T p.Val617Phe, in the Janus kinase 2 (JAK2) gene, which can give rise to acute and chronic myeloproliferative diseases." (PMID 32397294, 2020). "CALR alongside JAK2 and MPL mutations are included as major diagnostic criteria for PMF by the World Health Organization (WHO) classification of myeloproliferative neoplasms." (PMID 32842500, 2020). "Inflammatory and oncogenic signaling, both known to challenge genome stability, are key drivers of BCR-ABL-positive chronic myeloid leukemia (CML) and JAK2 V617F-positive chronic myeloproliferative neoplasms (MPNs)." (PMID 32272770, 2020). "Gene knock-out studies together with evidence from patients carrying activating mutant forms of JAKs (eg, JAK2 V617F in myeloproliferative disorders) provided strong rationale for the development of JAK inhibitors." (PMID 32676568, 2020). "JAK2 rearrangements such as PCM1-JAK2 are frequently detected in myeloproliferative diseases with eosinophilia." (PMID 33505919, 2020). "Notwithstanding these concerns, several putatively selective JAK2 inhibitors have been developed and tested to treat myeloproliferative diseases." (PMID 32676568, 2020). "In some of these patients, a pathogenic, somatic variant in the Janus kinase 2 (JAK2) gene has been detected and in one case CTEPH and the myeloproliferative disease was diagnosed in the same patient at the same time." (PMID 32397294, 2020). "Ruxolitinib (Jakafi®, Incyte Corp.), a JAK1/JAK2 inhibitor, has been important in management of myeloproliferative neoplasms, such as myelofibrosis and polycythemia vera, in which gain-of-function mutations in JAK2 are found in 50–95% of patients." (PMID 31409327, 2019). "Cross-regulation of the MAPK and PI3K is affected by the presence of mutation of JAK2 (Janus kinase 2, JAK2-V617F) occurring in myeloproliferative neoplasms." (PMID 31652660, 2019). "Mutations in JAK2, Myeloproliferative Leukemia Virus (MPL), or Calreticulin (CALR) are detected in more than 80% of myeloproliferative neoplasm (MPN) patients, and these mutations are thought to play a significant role in the pathogenesis of MPN1–7." (PMID 30926777, 2019). "A prime example of the apparent paradox of healthy individuals carrying aberrations associated with myeloid malignancies, is the JAK2-V617F mutation, which has been considered to be the major culprit in causing polycythemia vera (PV) and other myeloproliferative neoplasms (MPN) for over a decade." (PMID 31398915, 2019). "Of nine patients with myeloproliferative neoplasm in the MVT group, eight (89%) were JAK-2 mutation positive." (PMID 30756343, 2019). "Janus kinase 2 (JAK2) inhibitors represent a promising therapeutic class of anticancer agents against many myeloproliferative disorders." (PMID 31805692, 2019). "Here, we report for the first time the effects of a novel natural product derivative, ZT55, a selective JAK2 inhibitor, on cells from patients with myeloproliferative disorders." (PMID 30717771, 2019). "Primary Myelofibrosis (PMF) is a myeloproliferative disorder associated with JAK2V617F, Calreticulin (CALR) indels, and MPLW515L/K mutations activating the tyrosine kinase JAK2 and its downstream signaling pathway." (PMID 31369569, 2019).
myeloproliferative neoplasm (continued). "First, formation of a mutant calreticulin is the critical lesion in up to half the patients with myeloproliferative neoplasms, MPN, and nearly all of the rest are due to a Jak2 activating mutation." (PMID 30097573, 2018). "Considering the previous findings in nonhematologic tissues, our research group identified a constitutive protein association between IRS2 and JAK2 in myeloproliferative neoplasm (MPN) models, which present constitutive JAK2 activation due to a V617F mutation." (PMID 30328953, 2018). "We also show that its expression is increased in both CD34+ circulating progenitors and in the serum of patients with JAK2-dependent myeloproliferative neoplasms with fibrosis." (PMID 29650953, 2018). "The activated JAK2-V617F mutant is very frequently found in myeloproliferative neoplasms (MPNs), and its inhibitor ruxolitinib has been in clinical use, albeit with limited efficacies." (PMID 29928488, 2018). "For instance, a gain-of-function JAK2 V617F somatic mutation constitutively activates the JAK-STAT pathway and is identified in the majority of patients with myeloproliferative neoplasm." (PMID 30262727, 2018). "The aim of this study was to compare the accuracy and clinical utility of qPCR and ddPCR applied at diagnosis and in MRD monitoring of JAK2 V617F-positive patients with myeloproliferative neoplasms." (PMID 30056580, 2018). "There are numerous natural products that are ER or SERCA targeted to be considered for applications in AML but also myeloproliferative neoplasms driven by JAK2 and MPL mutants." (PMID 30262727, 2018). "Fifteen SNPs (FDR < 0.1) near JAK2 (9p24) are associated with IBD, CD, UC, and several red blood cell traits; SLE, psoriatic arthritis and myeloproliferative neoplasms are other associations in the region." (PMID 29309429, 2018). "The role of JAK2 inhibitors like ruxolitinib and fedratinib has been studied in patients with myelofibrosis and myeloproliferative neoplasms (MPNs) that consistently exhibit dysregulation of the JAK1/JAK2 pathway." (PMID 29515770, 2018). "Mutations in genes coding for other JAK2 activators, like the TPO-R and G-CSF-R, have been found in myeloproliferative disorders." (PMID 29455651, 2018). "Germline variations at JAK2, TERT, HBS1L-MYB and MECOM have been found to associate with myeloproliferative neoplasms (MPNs) in European populations." (PMID 29100304, 2017). "Recently, JAK2V617F (a constitutively active JAK2 mutant) was shown to phosphorylates PRMT5 in myeloproliferative neoplasms." (PMID 28107179, 2017). "JAK2, which is again a non-receptor tyrosine kinase, plays essential roles in transmitting signals from multiple cytokine receptors, and constitutive activation of JAK2 has been demonstrated to result in myeloproliferative neoplasms." (PMID 29340070, 2017). "The ability to simultaneously detect JAK2 V617F and MPL W515K/L mutations would substantially improve the early diagnosis of myeloproliferative neoplasms (MPNs) and decrease the risk of arterial thrombosis." (PMID 28819248, 2017). "Previous reports have suggested that the overexpression of JAK2 is important in Hodgkin lymphoma and myeloproliferative neoplasms." (PMID 29029457, 2017). "In particular, gain-of-function mutations in the JAK genes, most frequently, V617F in the pseudokinase domain of JAK2, have been mapped in patients with blood disorders, including myeloproliferative neoplasms and leukemias." (PMID 29379470, 2017). "Janus kinase 2 (JAK2) has been regarded as an essential target for the treatment of myeloproliferative neoplasms (MPNs)." (PMID 28831147, 2017). "TG-101348 was developed as a selective inhibitor of JAK2 kinase for the treatment of myeloproliferative disorder." (PMID 28617226, 2017). "Very similar results were obtained by using the Jak1/Jak2 inhibitor ruxolitinib clinically in use for myeloproliferative neoplasms." (PMID 27286446, 2016).
myeloproliferative neoplasm (continued). "In conclusion, despite anticoagulation treatment, the recurrence rate after SVT in myeloproliferative neoplasms is high and suggests the exploration of new avenues of secondary prophylaxis with new antithrombotic drugs and JAK-2 inhibitors." (PMID 27813534, 2016). "Molecular studies of coexisting JAK2 V617F-positive myeloproliferative neoplasms and mature B cell malignancies indicate distinct disease entities arising in myeloid and lymphoid committed hematopoietic progenitor cells, respectively." (PMID 26904322, 2016). "Aberrant JAK2 signaling in myeloproliferative neoplasms has been also described to be dependent on lipid rafts." (PMID 27579617, 2016). "In this regard, activation of the IL6-Janus kinase 2 (JAK2)-STAT3 pathway has been observed in myeloproliferative disorders and ovarian cancer." (PMID 27409672, 2016). "A recent study demonstrated the potential of a specific inhibitor of BET proteins (iBET) to inhibit proliferation of myeloproliferative neoplasms driven by constitutively active Janus kinase 2 (JAK2)." (PMID 26483790, 2015). "JAK2 inhibition therapy is used to treat patients suffering from myeloproliferative neoplasms (MPN)." (PMID 26176817, 2015). "Multiple myeloma and JAK2 positive chronic myeloproliferative neoplasms are hematologic malignancies with a completely different cellular origin." (PMID 25914740, 2015). "Myeloproliferative neoplasms (MPNs) are the leading cause of Budd-Chiari syndrome (BCS), and the C allele of JAK2 rs4495487 was reported to be an additional candidate locus that contributed to MPNs." (PMID 26557140, 2015). "The Bcr-Abl oncoprotein is the driver mutation for chronic myelogenous leukemia (CML), and the Jak2(V617F) point mutation is strongly associated with acute myeloid leukemias (AML) and myeloproliferative diseases (MPD’s)." (PMID 25809097, 2015). "For example, the score between Budd-Chiari (MIM: 600880) syndrome and Myeloproliferative disorder (MIM: 131440) is in the 97th percentile and genes associated to these diseases have in vivo verified first-level interactions (JAK2 – PDGFRB)." (PMID 26631976, 2015). "CDC25A is also constitutively expressed downstream of oncogenic tyrosine kinases, including NPM-ALK and BCR-ABL, as well as JAK2 V617F in myeloproliferative neoplasms." (PMID 26515730, 2015). "Inhibitors of JAK2 kinase are emerging as an important treatment modality for myeloproliferative neoplasms (MPN)." (PMID 24830942, 2014). "The identification of JAK2/MPL mutations has been essential for the diagnosis of myeloproliferative neoplasms, however, around 30–45% of ET and PMF remain wild-type for JAK2/MPL, and, in some this cases, diagnosis is difficult." (PMID 25068507, 2014). "Background and Objective: Co-existence of myeloproliferative disorders (MPD) and Janus associated kinase 2 mutation (JAK2 V617F) is a well-established fact." (PMID 24639858, 2014). "There are currently no reported cases with the diagnosis of simultaneous plasma cell myeloma, chronic myelogenous leukemia, and Jak2 positive myeloproliferative disorder." (PMID 25386371, 2014). "Homozygosity of JAK2 V617F and of FLT3 mutations is associated with a poorer prognosis of patients with leukemia or myeloproliferative disorders." (PMID 25373456, 2014). "JAK2 kinase activity is negatively regulated by its JH2 domain, in which a gain-of-function mutation is found in the majority of patients with myeloproliferative neoplasms." (PMID 23592968, 2013). "Constitutive activation of JAK2 either by chromosomal translocation or by gain-of-function mutations results in hematological malignancies including leukemias and myeloproliferative neoplasms (MPN)." (PMID 23592968, 2013). "Previously, a somatic JAK2 mutation was found in a high number of myeloproliferative neoplasm (MPN) patients, that is, nearly 100% of patients with polycythemia vera (PV) and about 50% of patients with essential thrombocytosis (ET) and primary myelofibrosis (PMF)." (PMID 23300995, 2013).